CDK4 (cyclin dependent kinase 4)
Diseases named in the same sentence as CDK4 in open-access papers (continued):
Sharing a sentence is not in itself a finding about the gene and the disease.
tumor (continued). "p16, Cyclin D1 and CDK4 are cell cycle regulatory factors, and their gene mutations or protein abnormalities are closely related to tumorigenesis, tumor development and progression in a variety of tumors." (PMID 23842094, 2013). "The p16INK4A protein product of the CDKN2A locus is known to be an important tumor-suppressor gene, which directly inhibits the kinases encoded by the oncogenes CDK4 and CDK6." (PMID 24345474, 2013). "Our data point towards loss of CDK4 inhibitor p16 is the genetic alteration in the hyperplasia to tumor transition in the AKT activated transgene." (PMID 20174572, 2010). "This mild tumor phenotype was enhanced when the mice were crossed with mice carrying an activating mutation of cdk4." (PMID 20174572, 2010). "Among this series of compounds, an iodine-containing analog (compound 30) has also been reported as a potent Cdk4-cyclin D inhibitor (IC50 5 nM) causing inhibition of tumor cell proliferation." (PMID 19551155, 2009). "If there is any CDK4 variant risk effect in tumor and/or cancer predisposition, it is likely too modest to be detected in the current dataset." (PMID 19327170, 2009). "The results indicate that in control tumour cells, both endogenous and exogenous p27 are associated with the CDK4 complex to a greater extent." (PMID 17088910, 2006). "In a multivariate analysis, both cyclin D1 and CDK4 immunoreactivities (P < 0.01) and tumour stage (P < 0.001) were recognized as independent risk factors." (PMID 10390005, 1999). "We have recently demonstrated that immunosuppressive, IL17-secreting γδ T cells recruited to the tumor microenvironment by a CCL2-dependent mechanism upon CDK4/6 inhibition can repolarize tumor-associated macrophages toward a CX3CR1+ phenotype associated with resistance to therapy." (PMID 40662849, 2025). "The outcome of the Fisher's exact test revealed a significant correlation between CDK4 and OS event (p = 0.023); the chi-square test result revealed CDK4 to be significantly associated with T stage (p = 0.019), histologic grade (p = 0.004), and tumor status (p = 0.031)." (PMID 38231074, 2025). "Because bone marrow (BM) cells rely on RB for proliferation, CDK4 inhibitors may protect these cells while sparing RB-deficient tumour cells." (PMID 40478388, 2025). "As CDK4/6 inhibitors are indicated for patients with high-risk features, caution is warranted in extrapolating these findings to those with larger or grade 3 tumours." (PMID 40862813, 2025). "CDK4/6 inhibitors also promote antigen presentation by upregulating HLA class I molecules and inducing novel tumour-associated antigens, facilitating T-cell-mediated tumour clearance." (PMID 40563591, 2025). "Specifically, CDK4 amplification was linked to more aggressive tumor features—higher Breslow thickness, ulceration, mitotic rate, and clinical high-risk classification—as well as poorer MSS and DFS, underscoring its potential as a prognostic biomarker in ALM patients." (PMID 40362334, 2025). "Consequently, RB-deficient tumor models exhibit resistance to pharmacological inhibitors targeting CDK4/6, with these findings validated in multiple preclinical and clinical studies." (PMID 39924553, 2025). "Another tumour demonstrated partial KIAA1549 inversion in addition to CDK4 and KDM6B variants." (PMID 39948623, 2025). "MDK’s role in angiogenesis and therapy resistance has been confirmed through angiogenesis-related analyses associated with prognosis and tumor immune microenvironment, as well as single-cell RNA sequencing studies identifying molecular biomarkers predicting progression to CDK4/6 inhibition." (PMID 41139924, 2025). "Activating mutations in EGFR, typically characterized as late events, might lead to a tumor that is more associated with the AC-like state leading to redundancy in high CDK4 expression levels." (PMID 39959305, 2025).
tumor (continued). "In addition to CDK4 amplification, this patient’s tumor also harbored FGFR4 amplification, which has been associated with aggressive RMS behavior and therapeutic resistance." (PMID 40936693, 2025). "In addition, previous data have indicated that CDK4/6 inhibitors can influence cancer-associated immune responses within the TME by interacting with both tumour and immune cells." (PMID 41388212, 2025). "Despite the effective tumor-suppressing effects of CDK4/6 inhibitors, they may also cause harm to normal tissues and organs." (PMID 41282629, 2025). "Our data highlight baseline tumor-intrinsic and tumor microenvironments-associated indicators of CDK4/6i response in the "real-world" setting and offer implications for precision-based therapeutic combinations to enhance CDK4/6i efficacy." (PMID 40506447, 2025). "While changes in the cell cycle regulators, including the amplification of cyclin D, activation of CDK, and loss of p21CIP1 or p27KIP1, may contribute to tumor adaptation to CDK4/6 inhibition, the main resistance is mediated by RB1 inactivation." (PMID 38927958, 2024). "In depth knowledge of tumor mutations and resistance mechanisms may allow the selection of patients who could benefit from continuing with CDK4/6is beyond progression." (PMID 38930141, 2024). "In addition, the downregulation of cyclin D1 and CDK4, which encode proteins that regulate the cell cycle, is associated with tumor progression." (PMID 38548549, 2024). "We wondered whether the tumours that express especially high p16/CDKN2A levels, as we observed them in CDK4 profile A tumours, might be associated with a different outcome." (PMID 36453028, 2024). "Even though we cannot totally exclude a loss of CDK4 phosphorylation during sample processing, these two samples could represent particular class A tumours." (PMID 36453028, 2024). "We discuss how PD-L1 and FOXM1, a tumor-promoting transcription factor, are functionally linked and may be key mediators of resistance to CDK4/6-MEK targeted therapies." (PMID 39347707, 2024). "Furthermore, the current study reported that RANK overexpression drives intrinsic resistance to CDK4/6i, which is associated with a decreased proliferation rate and an aberrant interferon response in tumor cells." (PMID 39070363, 2024). "Recent studies have suggested the use of CDK4/6 inhibition in treating SMARCA4-deficient tumours." (PMID 36883553, 2023). "Our data highlight the power of using spatial transcriptomics to characterise the response of a tumour to a targeted therapy and provide further insights into the molecular and cellular basis underlying the response and resistance to CDK4/6 inhibitors in SHH MB." (PMID 37127652, 2023). "Patients showing these features might be good candidates for CDK4/6 inhibitors, which we and others have shown to cause profound decreases in Ki67 in tumours showing incomplete suppression with an AI alone." (PMID 37419892, 2023). "As a result, cell cycle-associated ncRNAs may act as predictors of CDK4/6 inhibition efficacy and perhaps present novel candidates for tumor therapy and diagnosis." (PMID 37240281, 2023). "Collectively, these data indicated the increased infiltration and activation of CD8+ T cells in tumor microenvironment might be responsible for the enhanced anti-tumor immunity associated with Cdk4 deficient cancer cells." (PMID 37833461, 2023). "CD8+ T cell depletion could totally reverse the anti-tumor effect of Cdk4 knockout, demonstrating the crucial role of CD8+ T cells in anti-tumor immunity observed in Cdk4 deficient tumors." (PMID 37833461, 2023). "Additionally, in IHC experiments, GAA suppressed the expression of protein markers associated with tumor progression, including Ki67, CDK4, and CDK6." (PMID 37496051, 2023).
tumor (continued). "In the most recent study, MEK inhibitors alone were ineffective, but low-dose combinations of a MEK inhibitor (mirdametinib) and CDK4/6 inhibitor (palbociclib) acted synergistically in causing remarkable tumor regression and improved survival in immune competent mice bearing MPNSTs." (PMID 37686402, 2023). "In contrast, combining CDK4/6 inhibitors can cause cell arrest in the G1 phase to increase olaparib-induced DNA damage in the G2 phase, strongly inhibit olaparib resistance, and improve anti-tumor efficacy." (PMID 37305685, 2023). "Further understanding of tumor mutations and mechanisms of resistance to endocrine resistance may allow us to target patients who would benefit from continuing CDK4/6i." (PMID 36980743, 2023). "Thus, genomic-independent mechanisms, potentially through the activation of distinct CDK/cyclin complexes, modulate Rb activity and a tumor’s susceptibility to CDK4/6 inhibition." (PMID 36797347, 2023). "Analysis of tumor samples and circulating tumor DNA (ctDNA) of patients receiving CDK4/6i plus ET have shown loss of RB1 at baseline or with treatment is associated with shorter progression-free survival (PFS), although such alterations appear uncommon, occurring in < 10% of resistant samples." (PMID 37475004, 2023). "Moreover, there were more infiltration of effector T cells marked as CD8+IFN-γ+ and CD8+GZMB+ in Cdk4 deficiency tumor tissues as compared with tumors derived from the corresponding parantal cancer cells." (PMID 37833461, 2023). "Interestingly, tumors grew to similar sizes in nude mice injected with either control or Cdk4−/− MCA205 and TC-1 cells, suggesting that the reduced tumor growth of Cdk4 deficient MCA205 and TC-1 cells was immune-dependent." (PMID 37833461, 2023). "Additionally, analysis of circulating tumor DNA (ctDNA) from BC patients that had disease progression on CDK4/6i revealed the acquisition of RB1 loss-of-function mutations in some of these patients." (PMID 37835528, 2023). "Therefore, CDK4/6 inhibition can cause genotoxic stress in a wide variety of tumour types, and this can occur during periods of continual drug treatment, as long as cell cycle progression is not completely inhibited during that time." (PMID 35037284, 2022). "Notably, this region hosts the RB1 locus, codifying a crucial tumor-suppressor whose loss is associated with resistance to anti-CDK4/6 therapies in ER-positive BC." (PMID 36010918, 2022). "So as the main mechanism underlying G1-targeted CDK4/6 inhibitors go through avoiding RB1 tumor suppressor phosphorylation and its subsequent inactivation, the effects of some agents such as palbociclib require the presence of a functional pRb protein to work properly." (PMID 35681689, 2022). "When CDK4/6i were developed and tested in preclinical studies, cell lines and xenografts representing the luminal BC subtype were shown to be most susceptible to proliferation arrest and tumor shrinkage." (PMID 35712501, 2022). "Thus, tumor tissue editing provides the basis of repurposed CDK4/6 inhibitors associated with strong clinical activity." (PMID 35814409, 2022). "This suggests that appropriate combinations with CDK4/6 inhibitors in PDAC may enhance immune response in tumors with loss of CDKN2A through tumor-centric and possibly TME mechanisms." (PMID 35273962, 2022). "Tumor cell proliferation is caused by cyclin D mutation and overexpression, CDK4/6 overexpression, and p16INK4A mutation and underexpression, all of which are mediated by the activity of CDK4/6." (PMID 35681786, 2022). "In this regard, a study over 514 ALM samples identified that these tumours frequently display a dysregulated CDK4 pathway, a product of either gains of CDK4/CCND1 or loss of CDKN2A that, in turn, promote G1 to S cell cycle transition and thus contribute to tumour proliferation." (PMID 32330367, 2021).
tumor (continued). "An association between Rb loss of function and resistance to combined CDK4/6i and ET was also observed in 3 patients with ER+/HER2− ABC who received CDK4/6i (palbociclib or ribociclib) and showed somatic mutations in Rb in circulating tumor DNA (ctDNA) upon disease progression." (PMID 34771560, 2021). "As a consequence, these tumor cells are considered susceptible to CDK4/6-targeted inhibition." (PMID 33467099, 2021). "The overexpression of CDK4 and cyclin D1 in combination was also associated with advanced tumor." (PMID 34395284, 2021). "In addition, the presence of acquired mutations in RB1, identified in circulating tumor DNA (ctDNA), has also been associated to clinical resistance in BC patients treated with CDK4/6i." (PMID 32899866, 2020). "Cyclin D-CDK4 complex was also reported to play a role in reducing the expression of PD-L1; therefore CDK4/6 inhibitors could promote expression of PD-L1, causing tumor immune evasion." (PMID 32899866, 2020). "CDK4/6 inhibitors hinder the transition from G1 phase to S phase by inhibiting Rb phosphorylation and E2F release and induce tumor cycle arrest at G1 phase, which can inhibit tumor cell growth and cause tumor regression." (PMID 32357912, 2020). "Moreover, tumor biopsy specimens from patients associated with changes in ER/PR levels showed resistance to CDK4/6 inhibitors mediated by low ER/PR expression." (PMID 33364954, 2020). "Other TNBC tumours with high RB expression, androgen receptor positivity, or associated clinical characteristics are also considered potential candidates and some pre-clinical research suggests a benefit of combination treatment including CDK4/6 inhibition." (PMID 31769425, 2019). "These patient tumor IHC data are in support of our in vitro findings and confirm that cyclin D1 deficiency and lower CDK4 expression is a unique feature of SCCOHT; these samples also retained the known RB/p16 profile associated with positive responses to palbociclib." (PMID 30718512, 2019). "This discrepancy between kinase inhibitor treatment and protein loss might indicate kinase-independent effects of CDK4/6 on tumor angiogenesis or additional effects on different pathways, e.g. apoptosis." (PMID 30858922, 2019). "Unchecked proliferation of Rb-positive tumor cells is commonly associated with mutations that dysregulate this pathway: including the overexpression of D-type cyclins, the mutation or overexpression of CDK4, or mutations in the INK4 family of CDK inhibitors." (PMID 29789718, 2018). "The present study aims to evaluate the efficacy of the CDK4/6 dual inhibitor, abemaciclib, in vitro and in vivo through evaluation of tumor reduction and associated pathway regulation to set the stage for clinical trial development to treat locally advanced EAC." (PMID 29245989, 2017). "Therefore, loss of CDK4 results in cell cycle arrest and tumor cell senescence, while loss of CDKN2B maintains cell cycle progression and tumor cell growth." (PMID 29383146, 2017). "Since ERK increases cyclin D expression and increases entry into the cell cycle, we hypothesized that the combination of MEK inhibitors and CDK4/6 inhibitors would have synergistic antitumor activity and cause tumor regression in vivo." (PMID 27167191, 2016). "Moreover, cyclins D & E, E2F1 and CDK4 and 6, have all been previously observed to be associated with poor outcome in a number of other tumour types." (PMID 25738365, 2015). "Increased CDK4 activity due to activating mutations, gene amplification, or the inhibition of CDK4-inhibitory signals via the silencing of p16INK4a has been suggested as a tumor-initiating and/or tumor-promoting event in different tumor types." (PMID 26528855, 2015).
tumor (continued). "It is possible, however, that other CDK4 gene variants may potentially contribute to tumor/cancer risk predisposition as well as that any potential CDK4 variant association may be detected by using a larger dataset." (PMID 19327170, 2009). "However, more studies are warranted to establish the role of other CDK4 variants in tumor-cancer predisposition." (PMID 19327170, 2009). "Additionally, in immune-reconstituted xenograft models, combined PI3Kα and CDK4/6 inhibition has been associated with remodeling of the tumor immune microenvironment, including increased CD8+ T cell infiltration and enhanced cytotoxic effector markers (such as Granzyme B)." (PMID 41280894, 2025). "CDKN2A is a known tumor suppressor, and its loss may render sensitivity to CDK4/6 inhibitors." (PMID 40361368, 2025). "As CDK4/6 inhibition has systemic effects and pleiotropic roles in cellular processes, it remains unclear whether these immune-modulatory effects are directly linked to tumor intrinsic RB activation." (PMID 41326426, 2025). "In addition to their effects on DCs, CDK4/6 inhibitors modulate TAMs that are shifted from an M2-like phenotype typically associated with immunosuppression, toward an M1-like phenotype that conversely contributes to anti-tumour immunity." (PMID 41388212, 2025). "Indeed, clinical data showed that CDK4/6is could change the immune system to exert antitumor effects, while these changes also caused tumor resistance to CDK4/6i." (PMID 39593745, 2024). "Thus, the combination of PIN1- and CDK4-inhibitors achieves synergistic anti-tumor activity against Rb-proficient or -deficient TNBC in immune-compromised or -competent mice, with an excellent safety profile, making it a strong candidate for clinical development." (PMID 38622115, 2024). "Therefore, CDK4/6 inhibition or RB suppression might induce the undesirable activation of the NF-κB/PD-L1 pathway and cause an immune evasion of tumor cells." (PMID 37375731, 2023). "Therefore, double inhibition of PI3K and CDK4/6 in a syngeneic mouse model of TNBC was followed by a switch in the tumor-associated immune cells, with an increase in T-cells and mature NK cells, and a decrease of immunosuppressive monocytic myeloid-derived suppressor cells (mMDSC) and Tregs." (PMID 35712501, 2022). "Loss of p16ink4a’s function as a tumor suppressor may confer high sensitivity to CDK4/6 inhibitors." (PMID 34771512, 2021). "While direct short- and long-term effects of CDK4/6i’s on the cell cycle vanish, an experimental study on ductal BC recently uncovered that genes associated with differentiation, inflammation, IFNγ response, and antigen processing are preserved in tumor and TME after palbociclib treatment." (PMID 33161487, 2021). "In addition, the degrader BSJ-02-162 in the human mantle cell lymphoma cell line (Granta-519) may cause significant degradation of CDK4/6 and at the same time induce tumor cell G1 cell cycle arrest." (PMID 34249939, 2021). "Importantly, the observation that RB mutation is uncommon in NPC suggests that a blockade of CDK4/6 activity could abolish the dependency of this tumor type on the cyclin D1–RB pathway." (PMID 33243298, 2020). "In addition, insulin has also been shown to influence glucose metabolism through the regulation of cyclin D1-cyclin dependent kinase (Cdk) 4 activity, rendering hyperinsulinemia-associated tumor growth susceptible to CDK4 inhibitors in the context of liver cancer." (PMID 33604295, 2020). "CDK4/6 + ET demonstrates superior tumor reduction and safety, potentially enabling postoperative therapy de-escalation." (PMID 41685416, 2026). "In vivo experiments confirmed that CDK4 promoted cisplatin resistance and tumor growth of A498 cells, and this effect was validated under both CIS and GEM intervention." (PMID 42220427, 2026).